SFRP5 (secreted frizzled related protein 5)
Diseases named in the same sentence as SFRP5 in open-access papers (continued):
Sharing a sentence is not in itself a finding about the gene and the disease.
chronic kidney disease (3 papers, 2017 to 2026). Impairment of the renal function secondary to chronic kidney damage persisting for three or more months. "We observed significant differences in serum Sfrp5 concentration, in relation to age, among these patients with chronic kidney disease." (PMID 32491086, 2020). "One study reported that SFRP5 inhibited high phosphate-induced calcification of vascular smooth muscle cells which is a major cardiovascular risk factor in chronic kidney disease (CKD)." (PMID 28851362, 2017). "Similarly, hypermethylation of the SFRP5 gene was observed in renal tubular cells and a mouse model of indoxyl sulfate‐driven chronic kidney disease, leading to reduced SFRP5 expression, Wnt/β‐catenin activation, and fibrosis progression." (PMID 41541657, 2026). "This phenomenon suggests that Sfrp5 and Wnt5a might be involved in development and evolution towards end-stage renal disease." (PMID 32491086, 2020). "In addition, presence of Sfrp5 has been correlated with chronic kidney disease, and we also demonstrated that the serum levels of SFRP5 were higher in patients with chronic kidney disease than in healthy patients." (PMID 32491086, 2020). "However, there is a need to carry out complementary studies in order to demonstrate the participation of Sfrp5 and Wnt5a within the pathophysiology of chronic kidney disease." (PMID 32491086, 2020). "This coincided with what was reported in another study about a negative correlation between serum Sfrp5 levels and glomerular filtration rate in patients with chronic kidney disease." (PMID 32491086, 2020). "However, no studies on the participation of Sfrp5 and Wnt5a in patients with chronic kidney disease have been conducted." (PMID 32491086, 2020).
colorectal cancer (3 papers, 2022 to 2024). A primary or metastatic malignant neoplasm that affects the colon or rectum. "Additionally, SFRP5 hypermethylation has been associated with the risk of colorectal cancer, and this hypermethylation can lead to the activation of the Wnt signaling pathway, which is a key driver of CRC progression." (PMID 39202484, 2024).
ischemia (3 papers, 2021 to 2023). A hypoperfusion of the BLOOD through an organ or tissue caused by a PATHOLOGIC CONSTRICTION or obstruction of its BLOOD VESSELS, or an absence of BLOOD CIRCULATION. "The authors of that study used Sfrp5-knockdown mice and concluded that the loss of Sfrp5 induced larger infarct sizes, caused extravagant inflammation reaction, increased cardiomyocyte apoptosis, and decreased cardiac function following ischemia/reperfusion injury." (PMID 34568442, 2021). "Mechanistic studies have demonstrated that SFRP5 can inhibit myocardial inflammation and injury following a mouse model of ischemia/reperfusion injury, possibly exerting anti-inflammatory action via inhibition of Wnt5a." (PMID 37504530, 2023).
morbid obesity (3 papers, 2021 to 2024). An excess of body weight, normally defined as an individual with a body mass index greater than 35 or a body weight greater than one hundred percent of ideal body weight. "Sfrp5 concentrations increased significantly following weight loss in the subgroup of subjects with morbid obesity, consistent with the presence of low-grade inflammation in these patients." (PMID 39339733, 2024). "In the morbid obesity group, Sfrp5 correlated positively with IL-12 concentrations (r = 0.604, p < 0.05)." (PMID 39339733, 2024). "We demonstrated that Sfrp5 concentrations increased significantly in patients with morbid obesity after the lifestyle intervention program was implemented for 1 year." (PMID 39339733, 2024). "Plasma SFRP5 levels were determined by ELISA in women with normal weight (NW; n = 20) and morbid obesity (MO; n = 69)." (PMID 34198988, 2021). "Similarly, in our previous study, we evaluated SFRP5 serum levels and hepatic SFRP5, WNT5A and c-Jun N-terminal kinase (JNK), an intermediate of the noncanonical WNT5A pathway, mRNA expression in patients with morbid obesity (MO) and NAFLD." (PMID 36077270, 2022).
acute myeloid leukemia (2 papers, 2012 to 2025). Acute myeloid leukemia (AML) is a group of neoplasms arising from precursor cells committed to the myeloid cell-line differentiation. "In a study on acute myeloid leukemia, elevated methylation of SFRP5 was observed to upregulate MDR1 expression, leading to the development of multidrug resistance." (PMID 40301374, 2025).
colorectal tumor (2 papers, 2006 to 2014). "The importance of SFRP5 as a regulatory site in an epigenetic mechanism was recently shown with the demonstration that methylation and repression of the promoters for SFRP1, −2, −4, and −5 in colorectal tumor cells causes constitutive expression of Wnt signaling and enhances tumor promotion." (PMID 16733553, 2006).
depression (2 papers, 2021 to 2024). "Moreover, we found that downregulated genes in prefrontal cortex of CUMS group such as Sfrp5 and Angpt2, which were correlated with depression, were reversed by the probiotics." (PMID 38855745, 2024). "For instance, the oncogene S100A9 was upregulated while the tumor suppressor genes HDC, AKAP12, SFRP5, and ALOX15 were downregulated in depression groups." (PMID 34650925, 2021).
Hyperinsulinemia (2 papers, 2021). An increased concentration of insulin in the blood. "The aim of this study was to assess serum SFRP5 concentration in a young healthy population in relation to insulin sensitivity and its regulation by hyperinsulinemia and/or serum free fatty acids (FFA) elevation." (PMID 34184187, 2021). "In conclusion, the present study provided novel evidence that hyperinsulinemia decreases serum SFRP5 and that the concurrent elevation of FFA abolishes this effect, but Intralipid/heparin infusion alone does not regulate SFRP5 concentration." (PMID 34184187, 2021). "During hyperinsulinemia, we observed a marked decrease in serum SFRP5 concentrations." (PMID 34184187, 2021). "Whether SFRP5 responds to hyperinsulinemia or the inflammatory conditions accompanied with IR need to be considered." (PMID 34284806, 2021). "In response to hyperinsulinemia during 6-h HEC, circulating SFRP5 in 20 healthy subjects significantly dropped from 63.78 ± 20.35 pg/mL to 56.8 ± 18.46 pg/mL at 120 min (p = 0.02), then to 54.19 ± 21.73 pg/mL at 360 min (p = 0.001)." (PMID 34184187, 2021).
leukemia (2 papers, 2019 to 2025). A malignant (clonal) hematologic disorder, involving hematopoietic stem cells and characterized by the presence of primitive or atypical myeloid or lymphoid cells in the bone marrow and the blood. "Both deletion of UHRF1 or overexpression of its downstream target secreted frizzled-related protein 5 (SFRP5) resulted in the inhibition of leukemia cell proliferation, promoting cellular apoptosis and induction of cell cycle arrest." (PMID 40301374, 2025). "In fact, overexpression of β-catenin was observed in leukemia cells from patients with methylated SFRP5, and a demethylation compound recovered SFRP5 protein expression and reduced ABCB1 protein levels." (PMID 31921125, 2019).
melanoma (2 papers, 2022 to 2024). A malignant, usually aggressive tumor composed of atypical, neoplastic melanocytes. "Our findings indicate that Sfrp5pepD, derived from SFRP5, retains the Wnt inhibitory mechanism and effectively reduces melanin production in both melanoma cells and normal human melanocytes." (PMID 38920996, 2024). "Migration and invasion of human melanoma cell lines (GLL-19 cells) were attenuated by SFRP5, which was the extracellular regulator of the Wnt signalling pathway." (PMID 35955809, 2022).
metabolism (2 papers, 2018 to 2021). "SFRP5 is highly expressed in duodenum, pancreas, small intestine, moderately expressed in the lungs, liver, gall bladder, adrenal, prostate and stomach, and dysregulation of SFRP5 in pancreas contributes to insulin secretion or glucose metabolism disease." (PMID 34489867, 2021).
myocardial ischemia (2 papers, 2021 to 2022). A disorder of cardiac function caused by insufficient blood flow to the muscle tissue of the heart. "But, to our knowledge, only one report has addressed the effect of Sfrp5 on myocardial ischemia injury." (PMID 34568442, 2021). "It was found that SFRP5 could alleviate myocardial damage, pathological damage and fibrosis, and promote angiogenesis in diabetic mice with myocardial ischemia injury." (PMID 35506262, 2022).
ovarian tumor (2 papers, 2024). "An interesting experiment has evaluated the function of SFRP5 in drug resistance in ovarian tumor; based on this experiment, epigenetic silencing of SFRP5 results in hyperactivation of Wnt to mediate EMT via TWIST upregulation and increases AKT2 levels in favor of drug resistance in ovarian tumor." (PMID 38334836, 2024). "When BRCA2mt ovarian tumors were compared with BRCA1mt tumors, eight genes (NOTUM, SFRP5, RNF43, ZNRF3, DKK1, DKK4, NKD1, and AXIN2) that negatively regulate Wnt signaling were upregulated in BRCA2mt tumors." (PMID 39028933, 2024).
polyp (2 papers, 2008 to 2024). A usually exophytic mass attached to the underlying tissue by a broad base or a thin stalk. "DKK1 and DKKL1 showed a significant upregulation in polyp specimens, while WNT10B, GREM1, RSPO3, SFRP5, and GPC3 showed a downward trend." (PMID 38473810, 2024). "Similarly, CGI methylation of SFRP4, SFRP5 and WIF1 correctly identified 61.5% of polyp patients and 78.9% of neoplasia-free subjects (P=0.0167)." (PMID 18542073, 2008).
adenoma (1 paper, 2014). A neoplasm arising from the epithelium. "We discovered widespread hypermethylation of the Wnt antagonists SFRP1, SFRP2, SFRP5, DKK2, WIF1 and SOX17 in the transition from normal to adenoma with only the Wnt antagonists SFRP1, SFRP2, DKK2 and WIF1 showing further significant increase in methylation from adenoma to carcinoma." (PMID 25432628, 2014).
adenomyosis (1 paper, 2025). The growth of endometrial tissue inside the muscular wall of the uterine corpus. "Adenomyosis‐related pathways, such as leukocyte extravasation signaling, were mainly activated in SFRP5+ epithelial ecotypes." (PMID 40190183, 2025). "In the invaginating microenvironment, SFRP5+ epithelial ecotypes exhibited the greatest transcriptional changes between adenomyosis and the control group." (PMID 40190183, 2025). "To further investigate the correlation between the SFRP5+ epithelial ecotypes and adenomyosis, we employed MuSiC2 to estimate SFRP5+ epithelial ecotype proportions in bulk RNA‐seq data of adenomyosis epithelial organoids and found a higher proportion of SFRP5+ epithelial ecotypes within AM group." (PMID 40190183, 2025). "To summarize, SFRP5+ epithelial cells were a group of pro‐adenomyosis epithelial cells located in the basal layer of the endometrium, exhibiting increased proportion and activation of adenomyosis‐related pathways compared to that in the control group." (PMID 40190183, 2025). "Additionally, spatial transcriptomics revealed higher expression of IHH in SFRP5+ epithelial cells which were distributed in endometrial basalis in adenomyosis, which would have been hidden in bulk estimation." (PMID 40190183, 2025). "While in adenomyosis (group AM), IHH expression level abnormally increased in SFRP5+ epithelial ecotypes." (PMID 40190183, 2025). "In the invaginating microenvironment, SFRP5+ epithelial cells stimulated endometrium proliferation and angiogenesis through autocrine and paracrine of IHH, promoting adenomyosis development." (PMID 40190183, 2025).
adenovirus infection (1 paper, 2023). "Moreover, the presence of SFRP5 and TCF7 in the tan module suggests that the WNT signaling pathway may be involved in adenovirus infection." (PMID 37017816, 2023).
allergic rhinitis (1 paper, 2025). Inflammation of the nasal mucous membranes caused by an IgE-mediated response to external allergens. "This hypothesis is supported by previous research showing that SFRP5 expression is downregulated in allergic rhinitis, that may be attributed to DNMT3B-driven DNA methylation." (PMID 40595027, 2025).
bacterial sepsis (1 paper, 2022). "In summary, our data suggest that the release of the anti-inflammatory adipokine sFRP5 from mature adipocytes in humans is induced by DPP4i which might compensate the sFRP5 deficiency found in COVID-19, but not in bacterial sepsis." (PMID 36056109, 2022). "In our previous clinical study in human subjects suffering from bacterial sepsis we observed stable (not reduced) sFRP5 concentrations." (PMID 36056109, 2022).
bladder tumors (1 paper, 2012). "Another study demonstrated higher promoter CpG hypermethylation and lower expression of mRNA transcripts for sFRP-1, sFRP-2, sFRP-4, and sFRP-5, Dkk-3, and Wif-1 genes in bladder tumor compared with normal bladder mucosa showing an inverse correlation." (PMID 22325146, 2012). "The methylation levels of sFRP-2 and Dkk-3 were found to be significant independent predictors of bladder tumors, whereas with sFRP-1, sFRP-5, and Wif-1, a trend towards significance was found as independent predictors." (PMID 22325146, 2012).
breast tumours (1 paper, 2008). "In primary breast tumours, methylation frequencies of SFRP1, SFRP2, SFRP5 and DKK1 were 40, 77, 71 and 19%, respectively." (PMID 18283316, 2008).
cerebrovascular diseases (1 paper, 2025). "Research on SFRP5 has primarily focused on cardiovascular and cerebrovascular diseases, with limited studies on its role in tumors." (PMID 39729237, 2025).
chronic heart failure (1 paper, 2023). "Furthermore, SFRP5 has shown favorable effects on atherosclerotic cardiovascular disease and was increased in chronic heart failure." (PMID 36830849, 2023).
chronic hepatitis (1 paper, 2014). An active inflammatory process affecting the liver for more than six months. "Compared with HBV-associated chronic hepatitis patients (12.28±7.34 ng/ml), patients with liver cirrhosis exhibited lower serum SFRP5 levels (9.38±5.31 ng/ml) (P<0.05)." (PMID 25120720, 2014). "SFRP5 levels were found to be lower in HCC patients than in patients with only chronic hepatitis or HBV-associated liver cirrhosis." (PMID 25120720, 2014). "Therefore, it is possible that low levels of sfrp gene promoter methylation or the relatively low serum SFRP5 levels observed in HBV-associated chronic hepatitis and liver cirrhosis may serve as biomarker for the risk of developing HCC." (PMID 25120720, 2014).
colitis (1 paper, 2022). Inflammation of the colon. "Genes related to promoters differentially methylated uniquely in Dnmt3aΔIEC mice (e.g., Cdkn2c, Ccn5, Ctnnbip1, and Sfrp5) at day 5 after the initiation of DSS colitis were enriched in processes related to cell junction and cell proliferation." (PMID 36271073, 2022).
COVID-19 (1 paper, 2022). A disease caused by infection with severe acute respiratory syndrome coronavirus 2. "So far, we found that DPP-4 inhibitor treatment is associated with increased sFRP5 serum concentrations and that COVID-19 is related to sFRP5 deficiency." (PMID 36056109, 2022). "In summary, our data suggest that DPP4i increase serum levels of anti-inflammatory sFRP5 which might be beneficial in COVID-19, reflecting a state of sFRP5 deficiency." (PMID 36056109, 2022). "Of interest, we found that subjects with COVID-19 revealed significant lower sFRP5 levels compared to healthy controls (p < 0.01)." (PMID 36056109, 2022). "We observed significant lower sFRP5 levels in COVID-19 patients compared to healthy controls, while Wnt5a levels were significantly increased in COVID-19 patients." (PMID 36056109, 2022). "This is of interest, since in the present analysis sFRP5 concentrations were reduced in severe COVID-19 disease, suggesting differences of sFRP5 in bacterial versus COVID-19 acute systemic inflammation." (PMID 36056109, 2022). "We therefore examined sFRP5 levels in patients hospitalised for severe COVID-19 and found significant lower levels compared to healthy controls." (PMID 36056109, 2022). "Having found that anti-inflammatory sFRP5 is increased in DPP4i treated T2D subjects we next examined, if sFRP5 and Wnt5a are altered in COVID-19 patients." (PMID 36056109, 2022). "Since sFRP5 might consequently be a molecular link for the beneficial effects of DPP4i in COVID-19, we further aimed to identify the exact source of sFRP5 in adipose tissue on cellular level." (PMID 36056109, 2022). "Furthermore, it might be of interest how sFRP5/wnt5a levels act in subjects with mild COVID-19 to prevent a possible more severe course of disease or post covid-19 symptoms." (PMID 36056109, 2022). "In addition, it might be speculated that elevated levels of sFRP5 might be an indication for a better clinical outcome of COVID-19 in obese as well as T2D patients, which could be interesting to examine in future biomarker studies." (PMID 36056109, 2022).
endometrioid carcinomas (1 paper, 2018). "In our series, hypermethylation of the Wnt antagonists (DKK1, DKK2, SFRP1, SFRP4, SFRP5, and WIF1) were observed with a significant prevalence in mucinous and endometrioid carcinomas." (PMID 29882921, 2018).
liver inflammation (1 paper, 2021). "In this regard, we observed decreased levels of mRNA abundance of SFRP5 in patients with liver inflammation than those without it." (PMID 34198988, 2021).
lung adenocarcinoma (1 paper, 2023). A carcinoma that arises from the lung and is characterized by the presence of malignant glandular epithelial cells. "Conversely, in patients with early-stage adenocarcinoma, the expression of the SFRP5 gene was significantly higher in tumour samples than in normal tissues, and the authors suggested the oncogenic role of SFRP5 in lung adenocarcinoma." (PMID 37999144, 2023). "Moreover, the mRNA analysis confirmed a lower expression of SFRP5 gene in different primary tumours, including lung adenocarcinoma and lung squamous, compared to normal tissues." (PMID 37999144, 2023).
oropharyngeal cancers (1 paper, 2015). Carcinoma, predominantly squamous cell, arising from the epithelial cells of the oropharynx. "In this regard, frequent hypermethylation of the negative regulators of this pathway (DKK-3, RUNX3, SFRP1, SFRP2, SFRP4, SFRP5, and WIF1) was observed in oral and oropharyngeal cancers." (PMID 25487617, 2015).
osteoporosis (1 paper, 2025). A condition of reduced bone mass, with decreased cortical thickness and a decrease in the number and size of the trabeculae of cancellous bone (but normal chemical composition), resulting in increased fracture incidence. "After the knockout of SFRP5, the protein expression levels of Wnt and β-catenin were significantly upregulated in rats with dexamethasone-induced osteoporosis." (PMID 39606935, 2025). "In a model of dexamethasone-induced osteoporosis, He and Gu confirmed the upregulation of SFRP5." (PMID 39606935, 2025). "RT-qPCR revealed that after the downregulation of SFRP5, the mRNA and protein levels of Runx2, ALP, and OPN in the femur and tibia of rats with dexamethasone-induced osteoporosis were significantly increased." (PMID 39606935, 2025).
peripheral arterial disease (1 paper, 2021). A disorder of the arteries supplying the upper and lower extremity and the visceral organs. "In the adipocytes of patients with the peripheral arterial disease (PAD), the plasma concentrations of WNT5A are significantly increased but those of SFRP5 are significantly decreased." (PMID 34948320, 2021).
preeclampsia (1 paper, 2022). Preeclampsia is a hypertensive disorder of pregnancy that is characterized by new-onset hypertension with proteinuria presenting after 20 weeks of gestation, and depending on mild or severe forms may initially present with severe headache, visual disturbances, and hyperreflexia. "SFRP4 and SFRP5 are observed to be upregulated in patients with severe preeclampsia." (PMID 35269385, 2022).